MPC1 (mitochondrial pyruvate carrier 1)
Description:
Mediates the uptake of pyruvate into mitochondria to maintain the balance between glycolysis and oxidative phosphorylation. Plays an essential role in cellular metabolism.
Synonyms: BRP44L; CGI-129; dJ68L15.3; SLC54A1; MPYCD
Tractability: Small molecule: a structure with a bound ligand is known. Antibody: UniProt predicts a signal peptide or a membrane-spanning region. PROTAC: its protein half-life has been measured.
Gene: Protein-coding gene on chromosome 6 (166,364,919 to 166,383,013, reverse strand). Ensembl gene ENSG00000060762.
Subcellular location: Mitochondrion inner membrane
Subcellular location (Human Protein Atlas): Mitochondria; Principal piece
Pathways (Reactome):
Metabolism: Pyruvate metabolism
Gene Ontology:
Molecular function: protein binding; pyruvate transmembrane transporter activity
Biological process: pyruvate import into mitochondria
Cellular component: mitochondrial inner membrane; mitochondrion
Genetic constraint (gnomAD): Loss-of-function variants: 7 observed, 14.3 expected, observed/expected ratio (o/e) 0.49, 90% interval 0.28 to 0.92. The upper end of that interval is the gene's LOEUF score, 0.92, which puts it in group 3 of 6, group 1 being the genes least tolerant of losing a copy. Missense variants: 114 observed, 140.68 expected, observed/expected ratio (o/e) 0.81, 90% interval 0.69 to 0.95. Synonymous variants: 47 observed, 49.56 expected, observed/expected ratio (o/e) 0.95, 90% interval 0.75 to 1.21.
Gene-disease validity (ClinGen):
ClinGen rates the evidence that MPC1 causes each of these diseases.
mitochondrial disease (autosomal recessive): Definitive.
Homologues: Orthologues: chimpanzee MPC1 (98% identical), guinea pig MPC1 (97% identical), rat Mpc1 (94% identical), tropical clawed frog mpc1 (83% identical), zebrafish mpc1 (82% identical), dog MPC1 (80% identical), rabbit MPC1 (77% identical), macaque MPC1 (74% identical), mouse Mpc1 (71% identical), Drosophila melanogaster Mpc1 (60% identical). Paralogues in human: MPC1L (60% identical), MPC2 (28% identical).
Diseases named in the same sentence as MPC1 in open-access papers:
MPC1 is named in the same sentence as 101 diseases in open-access papers, as found by Europe PMC text mining. Sharing a sentence is not in itself a finding about the gene and the disease. The quoted sentences say what the papers report.
prostate carcinoma (16 papers, 2015 to 2025). A carcinoma that arises from epithelial cells of the prostate gland. "Low MPC1 expression is associated with a poor prognosis in esophageal, gastric, colorectal, kidney, lung, and prostate cancers." (PMID 40746885, 2025). "Although MPC is formed by two subunits, previous studies indicated that the expression MPC1 subunit is specifically dysregulated and associated with poor prognosis in several cancers, including cholangiocarcinoma and prostate cancer." (PMID 38615083, 2024). "In prostate cancer, MPC1 deficiency significantly increases lactate production, glucose consumption, and glycolytic capacity." (PMID 34059057, 2021). "In renal clear-cell carcinoma, high MPC1 levels impair invasion in vitro and tumor growth in vivo, and are associated with increased overall survival, while in prostate cancer, Mpc1 KO cells show enhanced proliferative, migratory and invasive capacity." (PMID 33804985, 2021). "In prostate cancer patients, low MPC1 and high COUP-TFII expression were associated with metastasis." (PMID 32784379, 2020). "It was verified that MPC1 gene knockout caused metabolism reprogramming towards Warburg effect and unregulated the cell stemness in the prostate cancer cells in vitro." (PMID 28624784, 2017). "However, the role of MPC1 in prostate cancer and the underlying mechanism causing the down-regulation of MPC1 in tumor cells remain to be defined." (PMID 26895100, 2016). "Inhibition of MPC1 expression increases glycolytic metabolism in prostate cancer cells and promotes tumor malignancy." (PMID 40746885, 2025). "Research results also show that both MPC1 and MPC2 are low in prostate cancer, positively correlated with prognosis, and the loss of their expression results in more aggressive tumor cells." (PMID 40746885, 2025). "In prostate cancer, MPC1 expression was repressed by the transcriptional repressor of chicken ovalbumin upstream promoter-transcription factor II (COUP-TFII)." (PMID 38615083, 2024). "In prostate cancer, MPC1 expression is significantly decreased; this decrease is closely associated with unfavourable prognosis." (PMID 34059057, 2021). "Chicken ovalbumin upstream promoter transcription factor II (COUP-TFII), an MPC1 upstream regulator, represses MPC1 expression and facilitates growth and metastasis of prostate cancer cells." (PMID 34059057, 2021). "MPC1 repression is part of the metabolic switch toward increased glycolysis, which promotes prostate cancer cell growth and invasion." (PMID 32708919, 2020). "As with colon cancer, in prostate cancer cell lines, MPC1 knockout or chemical inhibition increases invasiveness, chemotherapy resistance, and stem cell marker expression." (PMID 32784379, 2020). "In cancer, upregulation of chicken ovalbumin upstream promoter-transcription factor II (COUP-TFII) transcript expression downregulates MPC1 expression to drive cell growth and metastasis in prostate cancer and glioblastoma." (PMID 32784379, 2020). "Wang and colleagues showed that MPC1 is transcriptionally repressed in human prostate cancer cells by the chicken ovalbumin upstream promoter-transcription factor II (COUP-TFII), a member of the steroid receptor superfamily." (PMID 32708919, 2020). "Knowing that mitochondria is essential to metabolism, we show herein that pyruvate transport blocking via deletion of the MPC1 gene has impact on the metabolism and biological behaviors in prostate cancer cells in vitro." (PMID 28624784, 2017). "In order to further explore the involvement of MPC in cancer biology, we performed MPC1 gene knockout in the murine prostate cancer cell line RM-1 with CRISPR/Cas9 technology." (PMID 28624784, 2017). "Here we report our results in a prostate cancer cell line in which the mitochondrial pyruvate carrier 1 (MPC1) gene was knockout." (PMID 28624784, 2017).
prostate carcinoma (continued). "To investigate the function of MPC1 in prostate cancer, we overexpressed MPC1 in prostate cancer cells using lentivirus delivered MPC1 with C terminal flag tag." (PMID 26895100, 2016). "Our findings reveal that COUP-TFII represses MPC1 expression in prostate cancer cells to facilitate a metabolism switch to increase glycolysis and promote cancer progression." (PMID 26895100, 2016). "To investigate how MPC1 is down-regulated in prostate cancer, we searched for the predicted transcriptional binding sites on the MPC1 promoter using PROMO TRANSFAC." (PMID 26895100, 2016). "As expected, MPC1 knockdown increased lactate production and glucose consumption in prostate cancer cells, hallmarks of increased glycolysis." (PMID 26895100, 2016). "Here, we show that MPC1 serves as a critical regulator of glycolysis in prostate cancer cells, which in turn controls cancer cell growth, invasion, and the tumorigenic capability." (PMID 26895100, 2016). "Knockdown of MPC1 in prostate cancer cells increased glycolysis and cell invasion, and more importantly abrogated the effect on glycolysis, cell growth and invasion upon COUP-TFII knockdown." (PMID 26895100, 2016). "We further demonstrate that COUP-TFII, which is upregulated in the prostate cancer patient, regulates MPC1 and glycolysis to promote tumor growth and metastasis." (PMID 26895100, 2016). "We chose MPC1 for further study because MPC1 is also down-regulated in prostate cancer tissues in other clinical datasets including GSE21034 and TCGA." (PMID 26895100, 2016). "There is a potential COUP-TFII binding site in the MPC1 promoter, and our ChIP assay confirmed binding of COUP-TFII at MPC1 promoter in prostate cancer cells." (PMID 26895100, 2016). "Taken together, these results indicate that MPC1 has a tumor suppressor function in prostate cancer cells." (PMID 26895100, 2016). "Our data indicate that COUP-TFII regulates prostate cancer metabolism through MPC1 to promote a more aggressive cancer phenotype." (PMID 26895100, 2016). "Consistent with the decreased MPC1 expression observed in patients, forced expression of MPC1 reduced cell growth of prostate cancer cells as indicated by BrdU incorporation." (PMID 26895100, 2016). "The MPC1 and MPC2 variants and their potential molecular and biological functions in human prostate carcinoma are currently under investigation in our laboratory." (PMID 27852261, 2016). "More importantly, patients having low levels of MPC1 expression showed poor prognosis in prostate cancer." (PMID 27852261, 2016). "In summary, we have described a role of COUP-TFII in regulating MPC1 expression and glycolysis in prostate cancer." (PMID 26895100, 2016). "The absence of the MPC1 gene causes cancer cell lines, specifically those from esophageal squamous cell carcinoma, prostate cancer, and pancreatic cancer, to resist radiotherapy and chemotherapy." (PMID 40746885, 2025). "MPC1 expression is significantly decreased in prostate cancer specimens." (PMID 34059057, 2021). "Increased MPC1 or MPC2 expression in prostate cancer patients predicts more favorable outcomes." (PMID 32784379, 2020). "Next, we investigated the effect of COUP-TFII and MPC1 on prostate cancer progression." (PMID 26895100, 2016). "To investigate whether MPC1 affects cancer invasion, we used a transwell chamber assay to measure the prostate cancer cell invasion ability." (PMID 26895100, 2016). "It is known that knockdown of MPC1 in prostate cancer cells increases glycolysis and cell invasion." (PMID 27852261, 2016). "In addition, increased expression of COUP-TFII was observed in prostate cancer patients and it is further increased in metastatic patients, which is consistent with the possibility of negative regulation of MPC1 by COUP-TFII." (PMID 26895100, 2016). "However, we were able to increase MPC1 protein levels when it was ectopically expressed alone in prostate cancer cells." (PMID 26895100, 2016).
prostate carcinoma (continued). "Another research team found that MPC1 expression is much lower in the primary tumors than in the normal adjacent benign prostate tissues, and is further down-regulated in metastatic prostate tumors, indicating that MPC1 down-regulation may predict a more aggressive prostate cancer." (PMID 27852261, 2016). "For example, MPC1 regulates mitochondrial respiratory capacity in renal cell carcinoma (RCC), prostate cancer, hepatocellular carcinoma (HCC), and cholangiocarcinoma." (PMID 34059057, 2021). "Conversely, downregulation of MPC1 expression by chicken ovalbumin upstream promoter-transcription factor II (COUP-TFII) leads to increased invasiveness and prostate cancer cell growth in culture." (PMID 32784379, 2020). "In the present study, we have demonstrated the mitochondrial location of both MPC1 and MPC2 proteins in the WT prostate cancer cells by IF and Western blotting." (PMID 28624784, 2017). "Interestingly, MPC1 is further down-regulated in metastatic prostate tumors in comparison to primary tumors, indicating that MPC1 down-regulation may predict a more aggressive prostate cancer." (PMID 26895100, 2016). "Linear regression analysis revealed that MPC1 expression level was positively correlated with MPC2 expression (r = 0.375, P = 0.006) in the prostate cancers." (PMID 27852261, 2016). "Firstly, we detected MPC1 and MPC2 expression in the two human prostate cancer cell lines by ICC and Western blotting, confirming the different expressions of MPC1 and MPC2 in various histological subtype derived cell lines." (PMID 27852261, 2016). "Alternately, there is a cell type specific difference in MPC1/MPC2 stability, since we also found that when MPC1 was knocked down, MPC2 expression remained unchanged in prostate cancer cells, suggesting the complexity of the MPC transporter." (PMID 26895100, 2016). "In this study, we verified variable MPC1 and MPC2 expressions in two different prostate cancer cell lines (LNCaP and DU145) and found that the aggressive DU-145 cell line expressed lower levels of MPC1 and MPC2." (PMID 27852261, 2016). "In this study, expression of MPC1 and MPC2 in LNCaP and DU145 prostate cancer cell lines was examined by immunocytochemistry (ICC) and Western blotting." (PMID 27852261, 2016). "ICC identified variable MPC1 and MPC2 protein expressions in the prostate cancer cell lines LNCaP and DU145." (PMID 27852261, 2016). "Among the glycolytic genes, we found the down-regulation of MPC1 (BRP44L), and the up-regulation of HK2 and GPI in prostate cancer, which also showed similar dysregulation patterns in other types of cancers." (PMID 26895100, 2016). "In prostate cancer cells, chicken ovalbumin upstream promoter-transcription factor II (COUP-TFII) inhibits the promoter activity of mitochondrial pyruvate carrier 1 (MPC1), leading to decreased mitochondrial pyruvate oxidation and a glycolytic metabolic phenotype." (PMID 40943457, 2025). "We further found that the MPC1−/− cells significantly increased glycolysis and cell invasion, which is consistent with the negative correlation between MPC1 expression and patient survival rate, indicating its tumor genetic role in prostate cancer." (PMID 28624784, 2017). "Taken together, these results indicate that regulation of MPC1 expression by COUP-TFII is not restricted to prostate cancer cells." (PMID 26895100, 2016). "We found that expressing MPC1 in prostate cancer cells reduced cell growth and invasion, which is consistent with the negative correlation between MPC1 expression and patient survival rate, indicating its tumor suppressor role in prostate cancer." (PMID 26895100, 2016). "The reason might be that prostate cancer cells already have elevated expression of endogenous MPC2, which could form functional transporter complexes with the ectopically expressed MPC1." (PMID 26895100, 2016). "However, the expression status of MPC1 and MPC2 in prostate cancer (PCA) is unclear." (PMID 27852261, 2016).
prostate carcinoma (continued). "MPC1 and MPC2 gene expressions were assessed in prostatic cancer cell lines LnCap, DU145 and PC3 firstly in our lab, and it was found that LnCap exhibited higher expression levels of MPC1 and MPC2 compared to DU145 and PC3 (Data not shown)." (PMID 26413751, 2015). "In conclusion, we have found low expression of MPC1 and MPC2 in agressive prostate cancer cell line, and also discovered that negative expression of MPC complex is significantly associated with unfavorable clinicopathological features in PCA samples and shorter survival in PCA patients." (PMID 27852261, 2016).
colon cancer (12 papers, 2016 to 2024). "Mitochondrial pyruvate carrier 1 (MPC1) has been reported to be downregulated in colon cancer and is associated with a poor prognosis." (PMID 35571098, 2022). "Loss of MPC1 blocks mitochondrial pyruvate oxidation, which facilitates aerobic glycolysis in colon cancer cells." (PMID 34059057, 2021). "In colon cancer cells, MPC1 deficiency promotes stem cell-like gene expression, whereas MPC1 overexpression inhibits stemness ability." (PMID 34059057, 2021). "In the contrary, lower MPC1 levels promote a glycolytic program associated with more rapid tumor growth in our model, consistent with observations from colon cancer cells." (PMID 33920080, 2021). "In colon cancer cell lines, knockdown of MPC1 or MPC2 promotes loss of cell–cell polarity, increases migration capacity, and drives resistance to radiation therapy." (PMID 32784379, 2020). "Re-expression of wild-type (WT) MPC1 and MPC2 in colon cancer cells, which carried mutations or deletions in the MPC1 gene, impaired colony formation in soft agar and spheroid formation in vitro and reduced tumor growth in vivo." (PMID 32708919, 2020). "Consistent with a causative role in tumorigenesis, re-expression of MPC1 repressed the Warburg effect in colon cancer cell lines." (PMID 28397687, 2017). "Consistent with our findings in OC, MPC1 downregulation-mediated suppression of MPC also promoted colon cancer cell growth both in vitro and in vivo." (PMID 38615083, 2024). "Recent studies have suggested that MPC1 functions as a repressor of the Warburg effect in colon cancer and is a marker that inversely correlates with stem cell properties." (PMID 33920080, 2021). "In this study, using chemical and genetic colon cancer mouse models, Mpc1 deletion in intestinal stem cells increased tumor formation and produced higher-grade tumors than Mpc1-positive stem cells." (PMID 32784379, 2020). "Earlier studies have reported that MPC1 is downregulated in colon cancer and its expression positively correlates with APC." (PMID 28397687, 2017). "In particular, recent studies reveal that colon cancer cells produce less of a protein called mpc1, which is involved in metabolism." (PMID 28397687, 2017). "Additionally, in a mouse model of colon cancer, Mpc1 ablation in intestinal stem cells leads to the preferential use of the long-chain fatty acid palmitate in intestinal crypts, while adenomas utilize glutamine." (PMID 37249600, 2023). "Consistent with this conclusion, the study of Takaoka and collaborators found that, in pancreatic and colon cancer cells, EMT was induced following suppression of MPC1 expression." (PMID 32708919, 2020). "For example, it was reported in colon cancer that both expressions of MPC1 and MPC2 are decreased in tumor tissues as compared with normal counterparts." (PMID 38615083, 2024). "It is not clear how MPC1 is regulated or how its activities relate to the known genetic events that contribute to colon cancer development." (PMID 28397687, 2017). "Interestingly, down-regulation of MPC1 has been shown in many cancers, and co-expression of MPC1 and MPC2 inhibits colon cancer cell growth." (PMID 26895100, 2016).
colorectal cancer (9 papers, 2015 to 2024). A primary or metastatic malignant neoplasm that affects the colon or rectum. "MPC1 also functions as a clinical indicator of cancers, including lung cancer, gastric cancer, colorectal carcinoma (CRC), intrahepatic cholangiocarcinoma (ICC), RCC, and glioblastoma (GBM)." (PMID 34059057, 2021). "Increased levels of pyruvate in JIMT1 cells due to GYY4137 treatment might be attributed to the reduction in mitochondrial import of pyruvate due to low expression of mitochondrial pyruvate carrier 1, as it was described in colorectal cancer cells." (PMID 38927055, 2024). "MPC1 and MPC2 gene expression has been investigated in cell lines like embryonal, heatologic, ovarian and colorectal cancer cell lines." (PMID 26413751, 2015). "In colorectal cancer (CRC) cells, an increase in aerobic glycolysis and downregulation of the TCA cycle can be attributed to the reduction in mitochondrial import of pyruvate due to low expression of mitochondrial pyruvate carrier 1 (MPC1)." (PMID 36618350, 2022). "Studies have shown that when overexpressing either MPC1 or MPC2 by itself in colorectal cancer cells, the protein fails to accumulate to a high level, suggesting that these two proteins might need to form a complex to be stable." (PMID 27852261, 2016).